H1-0 (H1.0 linker histone)
Description:
Histone H1 protein binds to linker DNA between nucleosomes forming the macromolecular structure known as the chromatin fiber. Histones H1 are necessary for the condensation of nucleosome chains into higher-order structured fibers and promote formation of the H3K27me3 mark by the PRC2/EED-EZH2 complex. The histones H1.0 are found in cells that are in terminal stages of differentiation or that have low rates of cell division.
Synonyms: H1F0; H1FV; H1.0; H10
Tractability: Small molecule: a structure with a bound ligand is known. PROTAC: ubiquitination databases record sites on it.
Target class: Other nuclear protein
Gene: Protein-coding gene on chromosome 22 (37,805,229 to 37,807,432, forward strand). Ensembl gene ENSG00000189060.
Subcellular location: Nucleus; Nucleus, nucleolus; Chromosome
Subcellular location (Human Protein Atlas): Nuclear bodies; Nucleoplasm; Actin filaments; Golgi apparatus
Pathways (Reactome):
Cellular responses to stimuli: Formation of Senescence-Associated Heterochromatin Foci (SAHF)
Programmed Cell Death: Apoptosis induced DNA fragmentation
Gene Ontology:
Molecular function: chromatin DNA binding; nucleosome binding; protein binding; RNA binding; structural constituent of chromatin; double-stranded DNA binding; nucleosomal DNA binding; DNA binding; minor groove of adenine-thymine-rich DNA binding
Biological process: chromosome condensation; heterochromatin formation; positive regulation of transcription regulatory region DNA binding; negative regulation of DNA recombination; nucleosome assembly
Cellular component: chromatin; chromosome; euchromatin; nuclear body; nucleoplasm; nucleus; transcription repressor complex; nucleolus; nucleosome
Genetic constraint (gnomAD): Loss-of-function variants: 5 observed, 9.24 expected, observed/expected ratio (o/e) 0.54, 90% interval 0.28 to 1.14. That is too few expected variants to judge how well the gene tolerates losing a copy. Missense variants: 231 observed, 260.43 expected, observed/expected ratio (o/e) 0.89, 90% interval 0.8 to 0.99. Synonymous variants: 143 observed, 109.9 expected, observed/expected ratio (o/e) 1.3, 90% interval 1.13 to 1.5.
Homologues: Orthologues: chimpanzee H1-0 (100% identical), macaque H1-0 (100% identical), pig H1-0 (96% identical), dog H1-0 (96% identical), guinea pig H1-0 (95% identical), mouse H1f0 (95% identical), rat H1f0 (86% identical), tropical clawed frog h1-0 (78% identical), zebrafish h1-0 (56% identical), Caenorhabditis elegans hil-3 (29% identical), Caenorhabditis elegans hil-5 (27% identical), Caenorhabditis elegans hil-4 (27% identical), and 2 more. Paralogues in human: H1-4 (47% identical), H1-5 (46% identical), H1-2 (44% identical), H1-3 (43% identical), H1-1 (43% identical), H1-6 (36% identical), H1-10 (33% identical), H1-8 (30% identical), H1-7 (18% identical).
Diseases named in the same sentence as H1-0 in open-access papers:
H1-0 is named in the same sentence as 57 diseases in open-access papers, as found by Europe PMC text mining. Sharing a sentence is not in itself a finding about the gene and the disease. The quoted sentences say what the papers report.
ovarian carcinoma (2 papers, 2023 to 2026). A malignant neoplasm originating from the surface ovarian epithelium.
tumor (22 papers, 2014 to 2025). "This notion is supported by reports indicating that other HDAC inhibitors, such as Trichostatin A (TSA) and sodium butyrate, have the capacity to induce expression of the differentiation-specific histone H10 in mouse and human tumor-derived cell lines." (PMID 34955095, 2021). "Restoration of BCL7A hindered cell proliferation in competition cell growth assay and xenograft tumor formation in vivo modulating significantly the expression of genes such as HMGCS1, H1-0, and IRF7, which may help to explain its tumor suppressor role in AML." (PMID 36941700, 2023). "Restoration of BCL7A expression in cell culture impaired cell proliferation in competition cell growth assay and tumor formation on xenografts in vivo, altering the expression of genes like HMGCS1, H1-0, IRF7, which may help to explain its tumor suppressor role in AML." (PMID 36941700, 2023).
H1-0 also shares sentences with these, for which no sentence is quoted: cancer (41 papers); breast carcinoma (18); infection (12); Alzheimer disease (4); melanoma (4); glioblastoma (3); leukemia (3); lymphoma (3); prostate carcinoma (3); autoimmune hepatitis (2); injury (2); leishmaniasis (2); neurodegenerative disease (2); Viral infection (2); allergic response (1); allergic rhinitis (1); autoimmune disorders (1); Autoimmunity (1); Burkitt lymphoma (1); cervical cancer (1); chronic lymphoid leukemia (1); cognitive decline (1); colon cancer (1); cutaneous leishmaniasis (1); diabetic retinopathy (1); fibrosarcoma (1); follicular lymphoma (1); gastric carcinoma (1); glaucoma (1); glioma (1).
A further 25 diseases each share a sentence with H1-0 in 1 paper.